CD160 (CD160 molecule)
Diseases named in the same sentence as CD160 in open-access papers (continued):
Sharing a sentence is not in itself a finding about the gene and the disease.
autoimmune disease (continued). "Therefore, CD160 plays an important role in the maintenance of immune tolerance and the prevention of autoimmune diseases." (PMID 34238277, 2021). "In our study, we found that CD160 was the most significant co-signaling gene aberrantly expressed in autoimmune diseases, while several widely-studied co-signaling genes, such as ICOS, PD1 and CLTA4, were not identified as significant genes in the RRA analysis." (PMID 30842773, 2019). "Findings from the RRA discovery study suggested that CD160 was the most significant gene aberrantly expressed in autoimmune diseases (Adjusted P = 5.9E-12), followed by CD58 (Adjusted P = 5.7E-06), CD244 (Adjusted P = 9.5E-05), LGALS9 (Adjusted P = 0.001) and CD27 (Adjusted P = 0.005)." (PMID 30842773, 2019). "Treatment strategy targeting CD160-related pathway may be promising for the therapy of autoimmune diseases." (PMID 30842773, 2019). "Moreover, future studies are recommended to explore the feasibility of treating autoimmune diseases by targeting CD160-related pathway." (PMID 30842773, 2019). "Besides, few studies have investigated the expression of CD160 in those autoimmune diseases using qRT-PCR or flow cytometry, and additional studies are needed." (PMID 30842773, 2019). "There are few studies focusing on the role of CD160 in autoimmune diseases." (PMID 30842773, 2019). "In addition, animals with knock-out of those members in the CD160/HVEM/LIGHT/BTLA signaling pathway could change the development or progression of autoimmune diseases, such as colitis and atopic dermatitis." (PMID 34238277, 2021). "Recent researches suggest that the CD160/HVEM/LIGHT/BTLA signaling pathway may contribute to the pathogeneses of autoimmune diseases, but the relationship between CD160 polymorphisms and autoimmune thyroid disease (AITD) has not been reported yet." (PMID 34238277, 2021). "Moreover, CD160 may be implicated in immune regulation in different types of disease, such as chronic viral infections (HIV, HCV), autoimmune diseases (e.g., psoriasis), and cancers." (PMID 30728903, 2019). "The findings from our study prove that CD160 rs744877 is related to GD, which adds new evidence for the roles of the CD160/HVEM/LIGHT/BTLA pathway in autoimmune diseases." (PMID 34238277, 2021). "A Cytoscape network diagram in our study showed that PD-L2 in PDAC is closely related to the expression of PD-L1, CD86, TNFRSF14, PD-1, CD160 and CTLA-4, which are important for the regulation of immunodeficiency and autoimmune diseases." (PMID 31464648, 2019). "The AUC of the ROC analysis for CD160 was generally less than 0.80, suggesting that it only had a moderate role in diagnosing autoimmune diseases and should not be used in a clinical setting as a sole diagnostic marker." (PMID 30842773, 2019). "Additionally, this study also suggest that CD160 has a moderate role in diagnosing SLE, IBD, JIA, and GD, suggesting that CD160 may be helpful for the diagnosis of autoimmune diseases." (PMID 30842773, 2019).
atherosclerosis (7 papers, 2015 to 2024). A disease characterized by the build-up of fatty material and calcium deposition in the arterial wall resulting in partial or complete occlusion of the arterial lumen. "Our results provide evidence that elevated CD160 expression on NK cells plays an important role in NK cell loss in atherosclerosis." (PMID 26071079, 2015). "In patients with atherosclerosis, increased expression of CD160 on NK cells stimulates the production of TNF-α, which leads to NK cell apoptosis and a subsequent decrease in the number of circulating NK cells." (PMID 35464400, 2022). "Notably, the expression of CD160 is significantly reduced in the mouse aorta as atherosclerosis progress." (PMID 39926714, 2024). "In patients with atherosclerosis, CD160 is significantly upregulated on peripheral NK cells; however, this effect may be offset by a concurrent decrease in the number of peripheral NK cells." (PMID 39926714, 2024). "The findings have motivated us to test the hypothesis that CD160 is involved in NK cell functioning in atherosclerosis." (PMID 26071079, 2015). "In summary, our results demonstrate increased expression of CD160 on NK cells from patients with atherosclerosis, which might indicate disease progression." (PMID 26071079, 2015). "Our data suggest that CD160 might be used as a potential indicator for atherosclerosis progression." (PMID 26071079, 2015). "CD160 engagement by both classical and non-classical MHC-I molecules mediates NK cell cytotoxicity and proinflammatory cytokine production of a unique profile (IFN-γ, TNF-α, and IL-6), all of which have been implicated in atherosclerosis." (PMID 26071079, 2015). "However, the mechanisms for CD160 induction and the exact role of CD160 in atherosclerosis are not clear and need to be further investigated, especially with animal models." (PMID 26071079, 2015).
chronic lymphocytic leukemia (7 papers, 2020 to 2025). "For example, CD160+CD8+ effector T cells increase in number in patients with chronic lymphocytic leukemia (CLL), which represent the phenotype of exhausted CD8+T cells." (PMID 41009359, 2025). "CD160 represents a valid therapeutic target as it has been shown to be expressed on chronic lymphocytic leukaemia cells and on the surface of newly formed vessels." (PMID 33154441, 2020). "CD160 is abnormally overexpressed in B-chronic lymphocytic leukemia (CLL), which is the most frequently diagnosed leukemia in developed countries." (PMID 36420268, 2022). "However, CD160 and TNFRSF14 are highly expressed in a variety of tumors (e.g. chronic lymphocytic leukemia and multiple myeloma) and promote tumor evasion of immune surveillance by regulating NK and T cell activity." (PMID 40342824, 2025). "CD160 is abnormally expressed in B-cell chronic lymphocytic leukemia (CLL) but not expressed in normal B lymphocytes." (PMID 36420268, 2022).
hepatocellular carcinoma (7 papers, 2021 to 2025). A malignant tumor that arises from hepatocytes. "We also observed expression of the activation marker, CD160, known to be enriched in NK cells identified in hepatocellular carcinoma, but also potentially a marker of early, tissue-resident ILC1 cells." (PMID 40443661, 2025). "Reduction in CD160 expression led to impaired NK cells and poor outcomes in Hepatocellular carcinoma patients." (PMID 37996402, 2023). "For hepatocellular carcinoma, the reduction in the number and function of CD160 + NK cells in TME contributes to the immune escape." (PMID 35280985, 2022). "Reduced CD160 expression impaired NK cell function and had a poor clinical prognosis in hepatocellular carcinoma patients." (PMID 34553038, 2021). "In addition, intratumoural CD160+ NK cells were found to be more exhausted than peritumoural CD160+ NK cells in hepatocellular carcinoma and to produce less IFNγ." (PMID 36420268, 2022). "In patients with hepatocellular carcinoma (HCC), the intra-tumoral expression of CD160 is decreased in NK cells, but not in CD8+ T cells." (PMID 38612764, 2024).
breast carcinoma (6 papers, 2013 to 2024). "Indeed, in our study, genetically elevated circulating protein levels of CD160 are associated with a protective effect in breast cancer, suggesting that a drug activating CD160 specifically on NK cells may enhance anti-tumour immune responses in breast cancer." (PMID 37996402, 2023). "Of those, we present five proteins (CD160, DNPH1, LAYN, LRRC37A2 and TLR1) that show a potential causal role in breast cancer risk with confirmatory results in independent cohorts." (PMID 37996402, 2023). "To summarise, the MR analysis showed that genetic elevation of CD160, DNPH1, LAYN, LRRC37A2 and TLR1 associated with breast cancer risk, and with similar effects on ER+ and ER− cancers." (PMID 37996402, 2023). "In conclusion, by applying an MR approach to a broad range of circulating proteins we found that genetically elevated CD160, DNPH1, LAYN, LRRC37A2 and TLR1 were associated with breast cancer." (PMID 37996402, 2023). "We found that genetically lower levels of CD160 and LRRC37A2 and genetically higher levels of DNPH1, LAYN and TLR1 were associated with increased risk of breast cancer." (PMID 37996402, 2023). "Lead pQTL in cis-regions for CD160, LAYN and TLR1 were not the variants with the lowest p-values for breast cancer risk but were localised in the same, size-limited, genomic region." (PMID 37996402, 2023).
psoriasis (6 papers, 2019 to 2025). An autoimmune condition characterized by red, well-delineated plaques with silvery scales that are usually on the extensor surfaces and scalp. "CD161 serves as a marker for NK cells that can respond to IL-12 and IL-18 during differentiation, leading to the subsequent upregulation of NKp30, CD160, CD25, CD69, and IFN-γ—an identified psoriasis-associated pathogenic factor." (PMID 38596682, 2024). "In previous studies, we demonstrated that CD160 has a coactivating function with the CD3 receptor in a minor subset of CD4+ CD160+ T cells isolated from inflammatory skin lesions in dermatitis and psoriasis samples." (PMID 36420268, 2022). "Recent study showed that the gene expression of CD160 and BTLA was significantly lower in psoriasis patients with health control." (PMID 34354596, 2021). "However, the mechanism that CD160/BTLA pathway acts as a role in the pathogenesis of psoriasis is not clear." (PMID 34354596, 2021).
colitis (5 papers, 2021 to 2025). Inflammation of the colon. "Furthermore, while the surface marker CD160 is preferentially induced by IL-23 on Th1-like cells, the absence of CD160 abolishes the pathogenic role of Th1-like cells in exacerbating colitis." (PMID 39379604, 2024). "In addition, in vivo studies have demonstrated that recipient animals that receive CD160-deficient Th1-like cells have strong protection against colitis and less inflammation." (PMID 36420268, 2022). "Moreover, a recent study showed that CD160 is upregulated in Th1-like cells through IL-23 activity and is implicated in the induction of intestinal inflammation during colitis." (PMID 36420268, 2022). "WB and immunofluorescence experiments confirmed that the expression levels of MMP-9, PTGDS, SLC26A8, and CD160 in colitis were significantly increased, whereas that of TLR5 were decreased." (PMID 36733384, 2022). "The expression of MMP-9, PTGDS, SLC26A8, and CD160 in colitis was increased in the IBD mouse model, whereas the expression of TLR5 was downregulated." (PMID 36733384, 2022). "Screening of disease markers for colitis in mice using a machine-learning approach revealed that the expression levels of SLC26A8, MMP9, PTGDS, and CD160 were significantly elevated in colitis tissues, whereas the expression level of TLR5 was significantly reduced." (PMID 40110435, 2025).
HIV-1 infection (5 papers, 2018 to 2024). The type species of lentivirus and the etiologic agent of acquired immunodeficiency syndrome (AIDS). "In contrast, another study proposed that the co-expression of CD160 and PD-1 defined an advanced exhausted T cell population during chronic HIV-1 infection." (PMID 33072082, 2020). "While the current results suggest that successful treatment of HIV-1 result in normalized levels of activated and exhausted CD8 T-cells, we have in another cohort found that memory CD8 T-cells expressing TIGIT, PD1, CD160 and 2B4 are increased in treated HIV-1 infection as compared to seronegative." (PMID 34712231, 2021). "To explore the function of CD160 in CD8+ T cells during chronic HIV-1 infection, we first examined the enrichment of CD160-positive CD8+ T cells from three groups: HIV-1-infected slow progressors (SP), HIV-1-infected typical progressors (TP), and HIV-seronegative individuals." (PMID 33072082, 2020). "Here we showed that CD160 defines a polyfunctional and proliferative CD8+ T cell subset with a protective role during chronic HIV-1 infection." (PMID 33072082, 2020). "In addition to displaying a TEMRA-like phenotype, Vδ1 T cells had elevated expression of CD160, TIGIT, and PD-1 indicative of in vivo activation occurring during the course of HIV-1 infection." (PMID 39149467, 2024).
Sepsis (5 papers, 2022 to 2025). Sepsis is defined as life-threatening organ dysfunction caused by a dysregulated host response to infection. "Although the precise role of CD160 in sepsis remains elusive, it has been implicated in fostering an amplified inflammatory response through its association with heightened cytokine secretion from NK cells, encompassing TNF-alpha, IFN-gamma, and IL-614." (PMID 38263335, 2024). "Our findings reveal a lower expression of CD160 in sepsis patients compared to controls, suggesting its utility as a negative prognostic indicator for sepsis." (PMID 38263335, 2024). "To further validate the diagnostic capability of the four genes CD160, CX3CR1, DENND2D, and FAM43A in clinical samples, we collected the 10 pairs clinical samples from the healthy and sepsis samples." (PMID 38263335, 2024). "We further explored the diagnostic ability of CD160, CX3CR1, DENND2D and FAM43A for sepsis in both training cohort and test cohort." (PMID 38263335, 2024). "Given the recognized association between CD160 expression and CD8+ T cell exhaustion, the diminished CD160 levels in sepsis patients might reflect the detrimental hyperactivation of the immune system characteristic of sepsis progression." (PMID 38263335, 2024). "The ROC curve results displayed that the AUCs of CD160, CX3CR1, DENND2D and FAM43A were 0.965, 0.986, 0.991 and 0.985 in the training cohort, and 0.773, 0.756, 0.660 and 0.721 in the test cohort, indicating a favorable diagnostic ability for sepsis." (PMID 38263335, 2024). "Furthermore, the conclusion that CD160 alleviates NKT cell exhaustion and its association with inflammation regulation for the treatment of YHJF in sepsis is currently supported only by animal experimental evidence and requires further validation through clinical trials." (PMID 41170288, 2025). "We selected four MAAGs—CD160, CX3CR1, DENND2D, and FAM43A—to construct a prognostic model for sepsis." (PMID 38263335, 2024). "The qRT-PCR results exhibited that the mRNA expression of CD160, CX3CR1, DENND2D and FAM43A were obviously down-regulated in the sepsis group which was consisted with previous results." (PMID 38263335, 2024). "In the two groups of different expression trend modules, the core genes such as CD160, GATA2, GNLY, IL2RB and TGFBR3 were downregulated in the sepsis group, while genes such as ELANE, IL1R1, TLR5, FCGR1A, MAPK14 and PCSK9 were upregulated." (PMID 35332254, 2022). "However, the precise compounds within YHJF that target CD160 on NKT cells to prevent their exhaustion and improve immune dysregulation in sepsis have yet to be identified." (PMID 41170288, 2025). "A lactylation-based prognostic model was developed, comprising eight key genes (CD160, HELB, ING4, PIP5K1C, SRPRA, CDCA7, FAM3A, PPP1R15A), and demonstrated strong predictive performance for sepsis outcomes (AUC = 0.78 in the training cohort; AUC = 0.73 in the validation cohort)." (PMID 40612938, 2025). "Ultimately, 8 key genes were identified: CD160, HELB, ING4, PIP5K1C, SRPRA (HR < 1); and CDCA7, FAM3A, PPP1R15A (HR > 1), and the hub genes showed apparent differences in expression between alive and dead sepsis patients." (PMID 40612938, 2025).
glioma (4 papers, 2020 to 2024). A benign or malignant brain and spinal cord tumor that arises from glial cells (astrocytes, oligodendrocytes, ependymal cells). "We found that TPM4 is related to the molecular targets of glioma, such as CD160, IDO1, IL10, KDR, PVRL2, and TGFB1." (PMID 36639743, 2023). "In newly diagnosed grade 3 gliomas, the descending frequency of expression was A2aR > PD-1 > CD39 > CD73 > TIGIT > LAG-3 > BLTA > CD160 > CTLA-4 > KIR > TIM3 on CD8+ T cells." (PMID 32721947, 2020).
multiple myeloma (4 papers, 2016 to 2025). "In our analyses both, CD160 and 2B4, were significantly upregulated on bone marrow T cells of myeloma patients suggesting that the extent of local immune suppression might be even higher than estimated from the previous investigations." (PMID 27809856, 2016). "Changes in T cell dynamics perhaps begin much earlier during the process of disease development in MM; we also observed an increased presence of CD8+ T cells expressing inhibitory receptors like CD152, CD160 and CD279 indicating suppression of productive CD8+ T cell response in multiple myeloma." (PMID 40641743, 2025). "Here, we assessed the expression of inhibitory molecules PD-1, CTLA-4, 2B4, CD160, senescence marker CD57, and CD28 on T cells of naive and treated myeloma patients in the bone marrow and peripheral blood and collected data on T cell subset distribution in both compartments." (PMID 27809856, 2016). "Therefore, we assessed surface expression of PD-1, CTLA-4, CD160, and 2B4, as well as expression of CD57 and CD28 in myeloma CD8+ T cells before and after therapy with immunomodulatory drugs and dexamethasone." (PMID 27809856, 2016). "Moreover, CD160 blockade has not been investigated in myeloma so far." (PMID 27809856, 2016).
Autoimmunity (3 papers, 2019 to 2022). The occurrence of an immune reaction against the organism's own cells or tissues. "Reduced CD160 expression in CD8+ T cells has been associated with autoimmunity." (PMID 35159987, 2022). "However, the molecular mechanism underlying the role of CD160 in autoimmunity is largely elusive, and additional studies are warranted to uncover it." (PMID 30842773, 2019). "The findings in the present study suggest the critical role of CD160 in the pathogenesis of autoimmunity." (PMID 30842773, 2019). "Some studies have indicated HVEM/CD160/BTLA/LIGHT pathway may has an important role in the etiology of autoimmunity." (PMID 30842773, 2019). "Collectively, the role of CD160 in the pathogenesis of autoimmunity is still largely rudimentary." (PMID 30842773, 2019). "The CD160/HVEM/LIGHT/BTLA pathway is an essential signaling pathway in regulating immunity, which is involved in the pathogeneses of infection and autoimmunity.." (PMID 34238277, 2021). "Thus, LIGHT is a critical controller of the BTLA/HVEM/CD160 network, and future investigation into LIGHT and its role in SjS are needed to fully understand the role of this pathway in SjS and other autoimmune conditions." (PMID 35159987, 2022).
Graves disease (3 papers, 2021 to 2025). Graves' disease is an autoimmune disorder that leads to overactivity of the thyroid gland (hyperthyroidism).It is caused by an abnormal immune system response that causes the thyroid gland to produce too much thyroid hormones. "Our findings add new data to the genetic contribution to Graves’ disease susceptibility and support the crucial role of the CD160/HVEM/LIGHT/BTLA pathway in the pathogenesis of Graves’ disease." (PMID 34238277, 2021). "Also, CD160 can be found, and its polymorphisms have been suggested to be related to Grave's disease, whose pathology is precisely the opposite of hypothyroidism." (PMID 39897058, 2025). "This is the first identification of the association of CD160 rs744877 with Graves’ disease." (PMID 34238277, 2021). "Furthermore, CD160 rs3766526 was not significantly related to either Graves’ disease or Hashimoto’s thyroiditis." (PMID 34238277, 2021).
leukemia (3 papers, 2015 to 2023). A malignant (clonal) hematologic disorder, involving hematopoietic stem cells and characterized by the presence of primitive or atypical myeloid or lymphoid cells in the bone marrow and the blood. "Expression levels of CD244 and CD160, which are expressed in severely exhausted T cells, did not significantly differ between non-leukemic mice and mice with advanced leukemia." (PMID 26658107, 2015).